TRIM51 (tripartite motif-containing 51)
Synonyms: SPRYD5; TRIM51A
Tractability: No criterion of Open Targets' tractability assessment is met for any kind of drug.
Gene: Protein-coding gene on chromosome 11 (55,883,297 to 55,891,810, forward strand). Ensembl gene ENSG00000124900.
Subcellular location (Human Protein Atlas): Vesicles; Nucleoli
Gene Ontology:
Molecular function: ubiquitin protein ligase activity; zinc ion binding
Biological process: innate immune response; regulation of gene expression
Cellular component: cytoplasm
Genetic constraint (gnomAD): Loss-of-function variants: 22 observed, 26.94 expected, observed/expected ratio (o/e) 0.82, 90% interval 0.58 to 1.17. The upper end of that interval is the gene's LOEUF score, 1.17, which puts it in group 5 of 6, group 1 being the genes least tolerant of losing a copy. Missense variants: 584 observed, 525.45 expected, observed/expected ratio (o/e) 1.11, 90% interval 1.04 to 1.19. Synonymous variants: 174 observed, 176.06 expected, observed/expected ratio (o/e) 0.99, 90% interval 0.87 to 1.12.
Homologues: Paralogues in human: TRIM51G (87% identical), TRIM49B (76% identical), TRIM49C (75% identical), TRIM49 (75% identical), TRIM49D1 (74% identical), TRIM49D2 (74% identical), TRIM43 (51% identical), TRIM43B (51% identical), TRIM64 (47% identical), TRIM64B (47% identical), TRIM64C (46% identical), TRIM77 (44% identical), and 68 more.
Diseases named in the same sentence as TRIM51 in open-access papers:
TRIM51 is named in the same sentence as 2 diseases in open-access papers, as found by Europe PMC text mining. Sharing a sentence is not in itself a finding about the gene and the disease. The quoted sentences say what the papers report.
viral infection (1 paper, 2020). "The small changes in driver proteins between the networks are seen in immunoregulatory proteins that are typically upregulated during viral infection (such as TRIM51 and MICA) and many of the proteins identified in the controllability analyses." (PMID 32993136, 2020).
TRIM51 also shares sentences with these, for which no sentence is quoted: melanoma (1 paper).